NEK5 (NIMA related kinase 5)
Tractability: Small molecule: a high-quality ligand is known; it belongs to a druggable protein family. PROTAC: a small molecule that binds it is known.
Target class: Other protein kinase NEK family; Kinase; Enzyme; Other protein kinase group; Protein Kinase
Gene: Protein-coding gene on chromosome 13 (52,033,611 to 52,129,092, reverse strand). Ensembl gene ENSG00000197168.
Subcellular location: Cell projection, cilium; Cell projection, cilium, flagellum
Subcellular location (Human Protein Atlas): Nucleoplasm; Cytosol
Gene Ontology:
Molecular function: protein kinase activity; ATP binding; protein serine kinase activity; protein serine/threonine kinase activity
Cellular component: cilium; sperm flagellum; motile cilium
Genetic constraint (gnomAD): Loss-of-function variants: 21 observed, 32.27 expected, observed/expected ratio (o/e) 0.65, 90% interval 0.46 to 0.94. The upper end of that interval is the gene's LOEUF score, 0.94, which puts it in group 3 of 6, group 1 being the genes least tolerant of losing a copy. Missense variants: 319 observed, 385.5 expected, observed/expected ratio (o/e) 0.83, 90% interval 0.75 to 0.91. Synonymous variants: 119 observed, 130.05 expected, observed/expected ratio (o/e) 0.92, 90% interval 0.79 to 1.07.
Homologues: Orthologues: chimpanzee NEK5 (79% identical), macaque NEK5 (77% identical), pig NEK5 (72% identical), rat Nek5 (52% identical), mouse Nek5 (51% identical), tropical clawed frog nek5 (50% identical). Paralogues in human: NEK3 (25% identical), NEK8 (19% identical), NEK11 (19% identical), NEK9 (18% identical), NEK2 (16% identical), NEK10 (15% identical), NEK6 (12% identical), NEK7 (12% identical).
Diseases named in the same sentence as NEK5 in open-access papers:
NEK5 is named in the same sentence as 18 diseases in open-access papers, as found by Europe PMC text mining. Sharing a sentence is not in itself a finding about the gene and the disease. The quoted sentences say what the papers report.
breast carcinoma (12 papers, 2019 to 2025). "Recently, NEK5 has been implicated by our group and others as an important driver in breast cancer migration, proliferation, and the epithelial-to-mesenchymal transition (EMT) process." (PMID 37046733, 2023). "Recent publications have demonstrated the association of NEK5 with poor prognosis and tumour progression in breast cancer." (PMID 36550548, 2022). "In support of this notion, doxycycline-inducible shRNA systems have demonstrated that NEK5 knockdown affects these traits in breast cancer cell lines, such as MDA-MB-231 and TU-BcX-4IC." (PMID 41154634, 2025). "For example, NEK5 promotes a mesenchymal and migratory phenotype in breast cancer, contributing to metastasis." (PMID 41154634, 2025). "NEK5 activity is known to regulated the mesenchymal and phenotype of breast cancer cells and can promote cell proliferation via the up-regulation of Cyclin A242,43." (PMID 38561388, 2024). "Altogether, NEK5 and breast cancer survival correlations is an example of the limitations associated with data generated by KMPlotter." (PMID 37046733, 2023). "In this study we have established a MCF-10A-based model for interrogation of NEK5 function in breast cancer and applied an integrated (phospho)proteomic approach to dissecting NEK5 signalling." (PMID 36550548, 2022). "The upregulation of NEK5 is significantly related to the progression and poor prognosis of breast cancer." (PMID 35105934, 2022). "Consistent with previously reported effects on cell proliferation and cell morphology in breast cancer, overexpression of NEK5 in the MCF-10A system enhanced acinar size in 3D culture, and led to an abnormal, rough acinar morphology." (PMID 36550548, 2022). "Specific members of the Nima-Related Kinase (NEK) family have been linked to cancer development and progression, and a role for NEK5, one of the least studied members, in breast cancer has recently been proposed." (PMID 36550548, 2022). "Overall, the study indicates that NEK5 impacts diverse pathways and processes in breast epithelial cells, and likely plays a multifaceted role in breast cancer development and progression." (PMID 36550548, 2022). "Specifically, Nek5 was shown to enhance breast cancer cell mesenchymal morphology and migration, and was also shown to enhance breast cancer cell proliferation via upregulation of Cyclin A2 expression, while downregulating Cyclin D1, D3, and E1 expression." (PMID 35409400, 2022). "In order to interrogate NEK5 function in breast cancer and the NEK5 signalling mechanism in breast epithelial cells via Bio-ID proteomics, we established MCF-10A immortalized mammary epithelial cells expressing a NEK5-BirA fusion protein." (PMID 36550548, 2022). "When NEK5 is silenced, it can significantly prevent the proliferation of breast cancer cells in vivo and in vitro, thus inhibiting their migration and invasion." (PMID 35105934, 2022). "We also determined to what extent the identified NEK5 interactors are co-expressed with NEK5 in breast cancer." (PMID 36550548, 2022). "This supports the relevance of the identified NEK5 interactome to breast cancer development and progression." (PMID 36550548, 2022). "Here, we established a new model system for NEK5 in breast cancer, demonstrating that NEK5 overexpression in MCF-10A immortalized human mammary epithelial cells enhanced clonogenicity and led to aberrant growth in 3D culture." (PMID 36550548, 2022). "Indeed, the elevated expression of NEK5 correlates with more aggressive tumor phenotypes, such as increased migration and invasion, especially in breast cancer cells." (PMID 41154634, 2025). "Overexpression of NEK5 has been reported in thyroid cancer and breast cancer." (PMID 37835513, 2023). "Emerging evidence supports a role for NEK5 in breast cancer development and progression." (PMID 36550548, 2022).
breast carcinoma (continued). "Overall this study indicates that NEK5 may play multiple roles in breast cancer development and progression and represents a potential target for therapeutic intervention." (PMID 36550548, 2022). "In breast cancer, NEK5-dependent CCNA2 overexpression promotes the proliferation of tumour cells." (PMID 31285741, 2019). "The expression of NEK2, NEK6, and NEK11 were related to colorectal cancer, NEK2, NEK3, NEK5, NEK6, and NEK8 to breast cancer, and NEK2 and NEK6 to prostate cancer." (PMID 31906878, 2020). "If this were the case, KMPlot’s mRNA data would not accurately reflect NEK5’s levels and activity in breast cancer cells." (PMID 37046733, 2023). "The mRNA level analysis of NEK genes in breast cancer cell lines and breast cancer patients from various data sources revealed that NEK2, NEK4, NEK5, NEK6, NEK8, and NEK11 are overexpressed in breast cancer and may be involved in breast cancer development." (PMID 37627077, 2023). "Interestingly, despite the literature and our experimental results demonstrating NEK5 to be a driver for TNBC function and progression, there is no statistical correlation between NEK5 mRNA expression and breast cancer survival based on the KMPlot data." (PMID 37046733, 2023). "It has been reported that in breast cancer, NIMA (never in mitosis gene a)-related kinase 5 (NEK5)-dependent CCNA2 overexpression encourages the proliferation of tumor cells." (PMID 36880057, 2023).
prostate carcinoma (4 papers, 2014 to 2022). A carcinoma that arises from epithelial cells of the prostate gland. "NEK5, one of the least studied of the family, has recently gained attention due to its potential involvement in breast and prostate cancer, although the signalling mechanisms and pathways utilized by NEK5 in these contexts remained poorly characterized." (PMID 36550548, 2022). "Transcriptome analyses of prostate cancer samples, benign, prostatic hyperplasia, and normal tissue, revealed, NEK5 and NEK2 are over-expressed in malignant tissue." (PMID 31906878, 2020). "The NEK5 gene has been reported to regulate prostate cancer and BC." (PMID 35368696, 2022).
benign prostatic hyperplasia (1 paper, 2020). A non-cancerous nodular enlargement of the prostate gland. "This did not occur until 2017, when, for the first time, NEK5 was shown to be overexpressed in an RNA-seq analysis of Russian patients with benign prostatic hyperplasia (BPH) and prostate cancer (PCa), and this was further validated by RTqPCR." (PMID 32294979, 2020).
breast tumors (1 paper, 2025). "For instance, DelSIEVE inferred that gene NEK1 and NEK5, which had been reported to be related to breast tumors, experienced both a deletion and a mutation on the trunk, resulting in all sequenced cells having genotype 1/-." (PMID 40855447, 2025).
kidney carcinoma (1 paper, 2020). Primary or metastatic malignant neoplasm involving the kidney. "In contrast, in thyroid and kidney carcinoma the level of NEK5 was higher than in normal tissues." (PMID 31906878, 2020).
lung carcinoma (1 paper, 2022). "Results showed that there was overexpression of NEK2/4/6/8, low expression of NEK1/3/7, and no expression of NEK5/9/10/11 in lung cancer." (PMID 35105934, 2022).
medullary thyroid carcinoma (1 paper, 2020). "In the broad spectrum TMA analysis (semiquantitative and quantitative), we observed an increased expression of NEK1, NEK2, NEK3, and NEK5 in papillary and medullary thyroid carcinoma." (PMID 31906878, 2020).
thyroid (1 paper, 2020). "The present study also aimed to investigate a possible role for NEK1, NEK3, and NEK5 in thyroid malignancy, and analyze their potential as diagnostic and prognostic markers." (PMID 31906878, 2020). "Here, we studied the expression of NEK1, NEK2, NEK3, and NEK5 in different types of normal and malignant tissues, using tissue microarray analysis, and identified NEKs as potential markers in thyroid malignancy." (PMID 31906878, 2020). "Once NEK1, NEK2, NEK3, and NEK5, all showed a higher level of expression in thyroid tumour tissue it was decided to expand the number of thyroid cases submitted to TMA analysis." (PMID 31906878, 2020).
triple-negative breast carcinoma (1 paper, 2023). An invasive breast carcinoma which is negative for expression of estrogen receptor (ER), progesterone receptor (PR), and human epidermal growth factor receptor 2 (HER2). "We and others recently reported NEK5 as a promoter of EMT, migration, and proliferation in Triple Negative Breast Cancers (TNBC)." (PMID 37046733, 2023).
cancer (8 papers, 2016 to 2025). A tumor composed of atypical neoplastic, often pleomorphic cells that invade other tissues. "This interplay suggests that targeting NEK5 and its associated kinases could provide therapeutic avenues for disrupting aberrant microtubule dynamics in cancer, potentially hindering tumor progression and metastasis." (PMID 41154634, 2025). "The associations of NEK5 with cancer also extend to stomach adenocarcinoma." (PMID 41154634, 2025). "For example, during cancer metastasis, NEK5 activity is coordinated with that of other NEK family members, such as NEK4 and NEK6, to orchestrate microtubule organization." (PMID 41154634, 2025). "Nonetheless, given its involvement in critical cellular processes and its upregulation in cancer, NEK5 represents a promising therapeutic target." (PMID 41154634, 2025). "These functions are particularly relevant in cancer cells, where the regulatory role of NEK5 is altered." (PMID 41154634, 2025). "Some studies have suggested that NEK5 is also related to the development of cancer and can interact with caspase-376." (PMID 35105934, 2022). "The objective of the present study was to understand the involvement of four members of the NEK family (NEK1, NEK2, NEK3 and NEK5) in different types of cancers by analyzing differential expression profiles through tissues microarray (TMA) assays." (PMID 31906878, 2020). "Significant increases in the protein expression levels of NEK1, NEK2, NEK3 and NEK5, were found in colon and lung in the normal vs. cancer tissues." (PMID 31906878, 2020). "Importantly, NEK5 is upregulated in various types of cancer, including breast, colon, stomach, lung, and thyroid cancers." (PMID 41154634, 2025). "However, its effects on cell proliferation and cancer progression appear to be cell type-specific, indicating that the role of NEK5 in cancer can vary depending on the cellular context." (PMID 41154634, 2025). "There are limited publications about the function and roles of NEK3, NEK4, and NEK5 in cancer." (PMID 37835513, 2023). "Bioinformatics tools and databases, such as the cancer cell line encyclopedia (CCLE) and tumor immune estimation resource (TIMER), suggest that NEK5 is differentially expressed in this cancer and could serve as a potential biomarker for prognosis and therapeutic targeting." (PMID 41154634, 2025). "Indeed, targeting NEK5 could potentially disrupt cancer cell migration and invasion, offering a strategy to combat metastasis in certain cancers." (PMID 41154634, 2025). "However, the different functions of NEK5 in both normal and cancer cells remain poorly understood." (PMID 36550548, 2022). "Given its relationship with cell cycle progression, NEK5 may also be a potential cancer biomarker." (PMID 32294979, 2020). "NEK5 is the least studied member of the family, but the reduced information may not reflect its importance, because NEK5 has been related to many hallmarks of cancer, including the context of cell death." (PMID 31906878, 2020). "Due to the lack of research on NEK5, its importance in the occurrence and development of cancer cannot be confirmed." (PMID 35105934, 2022). "In 2011, the correlation between the NEK family and cancer was demonstrated, but no recording of NEK5 was characterized." (PMID 32294979, 2020). "Our hit list contains genes coding kinases with established oncogenic functions such as MET, EGFR, AKT, mTOR, RSK2 as well as genes that do not (yet) have an established role in cancer progression (NEK5, SIK2)." (PMID 27374095, 2016). "No information is available about the protein levels of NEK5 in cancer and normal cells." (PMID 31906878, 2020).
tumor (6 papers, 2019 to 2025). "NEK5, on the other hand, showed high expression in patients with invasion and metastasis and in patients with tumour size > 4 cm." (PMID 31906878, 2020). "Additionally, the expression of NEK5 was related to the patient’s tumor size, showing higher expression with an increase in the tumor size." (PMID 32294979, 2020). "Additionally, according to the UALCAN database, the mRNA expression levels of NEK2, NEK3, NEK4, NEK5, NEK6, and NEK8 were significantly positively correlated with the tumour grade, whereas that of NEK10 was inversely associated with this factor." (PMID 38706902, 2024). "From the analysis of NEK5, it was possible to observe that the expression profile did not change between normal and tumour tissues, except that the thyroid (p < 0.05 –semiq.; p < 0.001-quant)." (PMID 31906878, 2020).
bacterial infection (1 paper, 2025). "The NEK5 and SLC25A15 genes encode proteins involved in mitochondrial function, cell-cycle progression, metabolism and tumourigenesis, but have no clear role in the immune response to bacterial infection." (PMID 40342962, 2025).
infection (1 paper, 2022). The state of being infected such as from the introduction of a foreign agent such as serum, vaccine, antigenic substance or organism. "As expected, D2C replication was significantly reduced in EID3 and NEK5 knockout cells compared to the parental Huh7.5.1 cells at both post-infection timepoints tested." (PMID 36514984, 2022). "Accelerated DENV2 replication damaged host DNA as mutant infection was dependent on host DNA damage repair factors, namely RAD21, EID3 and NEK5." (PMID 36514984, 2022).
NEK5 also shares sentences with these, for which no sentence is quoted: colorectal cancer (1 paper); lung squamous cell carcinoma (1); nasopharyngeal carcinoma (1); thyroid cancer (1); thyroid tumour (1).